SCML4 (Scm polycomb group protein like 4)
Description:
Putative Polycomb group (PcG) protein. PcG proteins act by forming multiprotein complexes, which are required to maintain the transcriptionally repressive state of homeotic genes throughout development (By similarity).
Synonyms: dJ47M23.1
Tractability: PROTAC: ubiquitination databases record sites on it.
Gene: Protein-coding gene on chromosome 6 (107,702,154 to 107,824,317, reverse strand). Ensembl gene ENSG00000146285.
Subcellular location: Nucleus
Subcellular location (Human Protein Atlas): Nucleoplasm
Gene Ontology:
Molecular function: chromatin binding; histone binding
Biological process: negative regulation of DNA-templated transcription
Cellular component: nucleus
Genetic constraint (gnomAD): Loss-of-function variants: 34 observed, 42.76 expected, observed/expected ratio (o/e) 0.8, 90% interval 0.6 to 1.06. The upper end of that interval is the gene's LOEUF score, 1.06, which puts it in group 4 of 6, group 1 being the genes least tolerant of losing a copy. Missense variants: 522 observed, 557.01 expected, observed/expected ratio (o/e) 0.94, 90% interval 0.87 to 1.01. Synonymous variants: 214 observed, 230.59 expected, observed/expected ratio (o/e) 0.93, 90% interval 0.83 to 1.04.
Homologues: Orthologues: chimpanzee SCML4 (99% identical), macaque SCML4 (98% identical), dog SCML4 (91% identical), pig SCML4 (90% identical), rat Scml4 (81% identical), mouse Scml4 (79% identical), tropical clawed frog scml4 (74% identical), guinea pig SCML4 (61% identical), zebrafish scml4 (53% identical), Drosophila melanogaster l(3)mbt (15% identical), Caenorhabditis elegans lin-61 (9% identical), Caenorhabditis elegans mbtr-1 (8% identical), and 1 more. Paralogues in human: SCMH1 (44% identical), SCML2 (34% identical), SFMBT2 (23% identical), SFMBT1 (21% identical), SCML1 (18% identical), PHC3 (16% identical), PHC1 (15% identical), PHC2 (15% identical), L3MBTL4 (13% identical), SAMD1 (12% identical), L3MBTL3 (11% identical), SAMD7 (11% identical), and 6 more.
Diseases named in the same sentence as SCML4 in open-access papers:
SCML4 is named in the same sentence as 10 diseases in open-access papers, as found by Europe PMC text mining. Sharing a sentence is not in itself a finding about the gene and the disease. The quoted sentences say what the papers report.
breast carcinoma (3 papers, 2019 to 2023). "SCML4 expression was shown to correlate with poor prognosis in breast cancer." (PMID 37197420, 2023). "SCML4 was reported to be downregulated in breast cancer stem cells." (PMID 31143705, 2019).
atherosclerosis (2 papers, 2019 to 2021). A disease characterized by the build-up of fatty material and calcium deposition in the arterial wall resulting in partial or complete occlusion of the arterial lumen. "SCML4 has shown association with coronary artery disease in a recent GWA study, and subsequent functional characterization suggested a role in atherosclerosis." (PMID 30796134, 2019). "But a study shown that SCML4 makes functional contributions to processes critical for atherosclerosis (endothelial cell activation and survival, inflammation, and adhesion) and decreased expression of SCML4 exacerbates endothelial dysfunction and vascular remodeling in a rat model." (PMID 34187403, 2021).
endothelial dysfunction (2 papers, 2020 to 2021). In vascular diseases, endothelial dysfunction is a systemic pathological state of the endothelium (the inner lining of blood vessels) and can be broadly defined as an imbalance between vasodilating and vasoconstricting substances produced by (or acting on) the endothelium. "We found that SCML4 is associated with endothelial dysfunction and vascular remodeling." (PMID 33023605, 2020).
lung adenocarcinoma (2 papers, 2021 to 2023). A carcinoma that arises from the lung and is characterized by the presence of malignant glandular epithelial cells. "Altogether, the results presented here indicate that KLRG1, BTK, CCR2 and SCML4 play important roles in the development of lung adenocarcinoma, and their expression can be effective biomarkers to predict LUAD patients’ survival." (PMID 34187403, 2021). "In this study, through the analysis of the database and clinical samples, we found four markers (KLRG1, BTK, CCR2 and SCML4) which may play important roles in the development of lung adenocarcinoma." (PMID 34187403, 2021).
allergic disease (1 paper, 2022). An immune response that occurs following re-exposure to an innocuous antigen, and that requires the presence of existing antibodies against that antigen. "Our study newly identified six loci associated with allergic diseases (MIIP, CXCR4, SCML4, CYP1B1, ICOS and LINC00824) and four pleiotropic loci associated with both autoimmune and allergic diseases (PRDM2, G3BP1, HBS1L and POU2AF1)." (PMID 35753705, 2022).
esophageal cancer (1 paper, 2024). A primary or metastatic malignant neoplasm involving the esophagus. "In the other clusters, the genes SCML4, HNRNPF, IFRD1, CSTA, ABL1, etc., have a causal relationship with esophageal cancer." (PMID 38434988, 2024). "Similarly, genes like SCML4, HNRNPF, IFRD1, CSTA, ABL1 in other immune cell clusters also exhibit a causal relationship with esophageal cancer." (PMID 38434988, 2024).
lung carcinoma (1 paper, 2023). "In addition, the roles of SETDB2, SNAI3, SCML4, ZNF540, and ETV1 were validated in multiple datasets and human lung cancer cell lines." (PMID 37197420, 2023).
tumor (4 papers, 2017 to 2023). "And a lower expression levels of KLRG1, BTK, CCR2, SCML4 were all associated with advanced neoplasm disease stage." (PMID 34187403, 2021). "Notably, the expression levels of KLRG1, BTK, CCR2, SCML4 were all associated with neoplasm disease stage (American Joint Committee on Cancer Code) (P = 0.001; P = 0.022; P = 0.004; P = 0.014, respectively)." (PMID 34187403, 2021). "With the exception of SCML4, the other three TFs of the immune response network were differentially expressed in tumours that took upon grafting." (PMID 28588211, 2017).
cancer (3 papers, 2018 to 2024). A tumor composed of atypical neoplastic, often pleomorphic cells that invade other tissues. "SCML4 is a transcription factor necessary for maintaining the multifunctionality of CD8+ T cells and is associated with a better prognosis in cancer patients." (PMID 38434988, 2024). "In this study, through the analyze of the data from the Gene Expression Omnibus, the Cancer Genome Atlas and the Genotype-Tissue Expression, we found that the expression of KLRG1, BTK, CCR2 and SCML4 was significantly downregulated in LUAD tissues compared to normal controls." (PMID 34187403, 2021).
SCML4 also shares sentences with these, for which no sentence is quoted: coronary artery disease (1 paper).